GSDME (gasdermin E)
Diseases named in the same sentence as GSDME in open-access papers (continued):
Sharing a sentence is not in itself a finding about the gene and the disease.
melanoma (continued). "Firstly, it was reported that GSDME who can be activated by Caspase 3 to mediate pyroptosis is expressed in the majority of melanomas." (PMID 34327145, 2021). "Taken together, it was indicated that a number of melanoma cells underwent Casp3/GSDME pathway-mediated pyroptosis and hence generated inflammatory cytokines to recruit immune cells." (PMID 34327145, 2021). "Specifically, killer cell GZMB directly cleaved GSDME at the same site as caspase-3 (Asp270) and induced caspase-independent pyroptosis in breast cancer and melanoma cells." (PMID 33634141, 2021). "Ectopic expression of GSDME in breast cancer and melanoma cells markedly repressed tumor growth in mice." (PMID 33634141, 2021). "Iron activates ROS for GSDME-dependent pyroptosis through a Tom20–caspase–GSDME pathway in melanoma cells." (PMID 34381023, 2021). "Chemotherapeutics, such as doxorubicin, lobaplatin, cisplatin and tetraarsenic hexoxide, can suppress the growth of neuroblastoma, melanoma, colon cancer cells and breast cancer by inducing GSDME‐mediated pyroptosis." (PMID 34590363, 2021). "Small molecular inhibitors, effecting on KRAS, EGFR, ALK in lung cancer 11, BRAF and MEK in melanoma cells 63, elicit concurrent GSDME-mediated PCD." (PMID 34335940, 2021). "Tom20 is oxidized by iron-activated ROS signaling and triggers pyroptosis of melanoma cells by inducing GSDME cleavages." (PMID 34381023, 2021). "Doxorubicin triggers GSDME-dependent pyroptosis in melanoma cell lines with high expression of GSDME." (PMID 32093389, 2020). "Researches have shown that BRAFi + MEKi treatment induces caspase-3 activation and increases cleavage of caspase-3, which promotes the production of the 35 kDa GSDME cleavage fragment in mouse and human melanoma cells." (PMID 33133646, 2020). "Targeted drugs induce GSDME-mediated pyroptosis in melanoma, linking the tumor-immune microenvironment with T cells-mediated anti-tumor immunity." (PMID 33133646, 2020). "At the same time, a decrease in GSDME mRNA expression level contributed to increased etoposide resistance in melanoma cells." (PMID 32341339, 2020). "Cytochrome c further activates caspase-3, and eventually induces the cleavage of GSDME and the pyroptotic death of melanoma cells." (PMID 31616642, 2019). "Based on the iron- and ROS-dependent features of pyroptosis in our study, unsurprisingly, such iron-related pyroptosis was specifically observed in tumor tissues, at least in melanoma that expresses GSDME." (PMID 30287942, 2018). "Tom20 further recruited Bax to mitochondria and caused cytochrome c release to cytosol, consequently activating caspase-3, and ultimately inducing the cleavage of GSDME and pyroptotic death of melanoma cells." (PMID 30287942, 2018). "Furthermore, vemurafenib 72 is a BRAF kinase inhibitor used to induce pyroptosis in melanoma through caspase-1/GSDME activation." (PMID 39316325, 2025). "Furthermore, Western blot analysis of the NTC-shRNA group revealed that TRI-03 treatment led to decreased levels of XIAP in melanoma tissue, as well as increased cleavage of GSDME and caspase-3." (PMID 40486906, 2025). "Caspase-3/GSDME-dependent pyroptosis in BRAF-mutant melanoma." (PMID 41235238, 2025). "Finally, doxorubicin 65 displayed their pyroptotic action on melanoma tumor cells via caspase-3/GSDME activation." (PMID 39316325, 2025). "Mechanistically, TRI-03 not only increases intracellular reactive oxygen species (ROS) levels by inhibiting TrxR1 activity but also decreases XIAP expression, leading to the activation of the caspase-9/caspase-3/GSDME axis and irreversible GSDME-mediated pyroptosis in melanoma cells." (PMID 40486906, 2025). "It is established that melanoma cells with GSDME defects create larger tumors than wild-type melanoma cells; thereby, GSDME might have anti-tumor activity." (PMID 39075259, 2024).
melanoma (continued). "Melanomas, characterized as “cold” tumors due to their poor response to ICIs, can be transformed into “hot” tumors through the induction of GSDME-related pyroptosis, especially in GSDME-expressing BRAFV600E/K mutant melanoma cells." (PMID 38304430, 2024). "In contrast to the lack of an effect mediated by iron supplementation on tumor growth reduction in GSDME-knockdown mice, iron-induced ROS production via iron dextran decreased melanoma growth in GSDMEwt mice, demonstrating that ROS-induced pyroptosis is GSDME dependent." (PMID 38336727, 2024). "Indeed, GSDME expression was shown to be suppressed in a variety of cancers (melanoma, colorectal cancer, and triple-negative breast cancer, etc.), and this tumor suppression was also mediated by killer cytotoxic lymphocytes." (PMID 38553639, 2024). "Since melanoma cells express a high level of GSDME, the iron-ROS-Tom20-Bax-Caspase-GSDME pathway could be a potential target for melanoma therapy." (PMID 39097717, 2024). "Very recently, another study confirmed that the GSDME-mediated pyroptosis is essential for initiating antibody recognition of intracellular antigens by inducing cell pyroptosis, inhibiting liver metastasis of circulating melanoma cells." (PMID 38104141, 2023). "Evidence confirmed that eEF-2K could amplify the pyroptosis-promoting impact of doxorubicin in melanoma cell lines expressing high levels of GSDME." (PMID 38104141, 2023). "GSDME is silenced by promoter hypermethylation and mutated in multiple cancers including gastric, breast, colorectal tumors and melanoma, suggesting GSDME could function in tumor suppression." (PMID 36742298, 2023). "Overexpression of caspase-3 and GSDME is often observed in pyroptosis-induced melanoma cells." (PMID 37373523, 2023). "As early as 2001, it was reported that melanoma clone cells transfected with gsdme cDNA displayed DNA fragmentation and the cleavage of caspase-3, indicating that GSDME might be connected with apoptotic pathways." (PMID 35462927, 2022). "However, in this study, GSDME was found to be more highly expressed in NPC cell lines compared to the A375 melanoma cell line, which is known to express GSDME." (PMID 36411454, 2022). "Decreased GSDME expression increases the acquired drug resistance of melanoma cells." (PMID 35480866, 2022). "Moreover, the sensitivity of Doxorubicin to melanoma cells was increased after silencing eEF-2K resulting in Doxorubicin-induced autophagy switching to GSDME-dependent pyroptotic cell death." (PMID 36071875, 2022). "Moreover, combined treatment with BRAF and MEK inhibitors induces GSDME-dependent pyroptosis in melanoma cells and subsequently increases the number of intratumoral CD8+ T cells." (PMID 35990696, 2022). "GSDME upregulation by decitabine may suppress tumor cell proliferation in gastric cancer, melanoma, and colorectal cancer, and inhibit the lymph node metastasis of breast cancer." (PMID 36177050, 2022). "In another mice model of melanoma, tumor growth surveillance results showed that the rate of GSDME-KO tumors formation and growth reaching the sacrifice threshold was markedly faster than that of GSDME-expressing tumors." (PMID 35462927, 2022). "Besides, DFNA5/GSDME acted as an antioncogene in hepatocellular cancer, and loss of DFNA5/GSDME contributed to drug resistance in melanoma and lung cancer." (PMID 35233921, 2022). "PD-L1 participates in the regulation of GSDME activation in melanoma cells." (PMID 35784685, 2022). "Recent studies showed that GSDME could be activated by caspase-3/-9 in lung cancer cells and melanoma." (PMID 35547808, 2022). "Moreover, iron-elevated ROS induced pyroptosis through activation of Bax/caspase-3/GSDME pathway by facilitating the oxidation of mitochondrial outer membrane protein Tom20 in melanoma cells." (PMID 33558527, 2021).
melanoma (continued). "Aside, it is worth mentioning that in a separate study, treatment-induced pyroptosis in melanoma cells via GSDME and caspase-3 accordingly promoted HMGB1 release and was directly tied to the infiltration of both tumor-associated T cells and activated dendritic cells." (PMID 34429144, 2021). "One of the latest updates in ROS-exploiting cancer therapy, in fact, identifies iron as an amplifier of ROS signaling to induce pyroptosis (a lytic programmed cell death initiated by inflammasomes), via the Tom20/Bax/caspase-3-cleaved gasdermin E (GSDME) pathway in melanoma cells." (PMID 33920160, 2021). "GSDME-mediated pyroptosis has also been found to be prompted in melanoma through a combination of BRAF and MEK inhibitors, causing immune cell infiltration/activation and melanoma regression." (PMID 34429144, 2021). "However, in neurofibroma SH-SY5Y or melanoma MeWo cells with high GSDME expression, traditional chemotherapeutic drugs such as doxorubicin, cisplatin can induce pyroptosis through caspase-3/GSDME pathway." (PMID 33718226, 2021). "A recent study suggested that blockade of the ERK1/2 pathway by targeted inhibitors could induce GSDME-mediated pyroptosis in melanoma cells." (PMID 33634141, 2021). "For example, Zhang et al36 indicated that GzmB, which is released from natural‐killer (NK) and CD8+ T lymphocytes, can directly cleave GSDME and consequently enhance the anti‐tumour immunity by activating GSDME‐mediated pyroptosis in breast cancer cells and melanoma." (PMID 34590363, 2021). "Melanoma with GSDME deletion is known to resist etoposide treatment." (PMID 34335940, 2021). "Moreover, overexpression of GSDME in melanoma and breast cancer cells significantly inhibited the growth of tumor xenografts in immunocompetent mice, while depletion of GSDME had the opposite effect." (PMID 33406603, 2021). "It has been shown that GSDME mediated doxorubicin-induced pyroptosis in melanoma cells." (PMID 32340261, 2020). "As GSDME is expressed in the majority of melanomas, it may be an opportunity for exploiting pyroptosis as an alternative anti-melanoma therapeutic strategy." (PMID 32340261, 2020). "In addition, the positive correlation between GSDME mRNA level and the chemotherapy sensitivity of melanoma cells was also demonstrated in a recent study." (PMID 31616642, 2019). "Lastly, using an in vivo mouse model of melanoma, we demonstrate that GSDME may possess a bona fide tumor suppressor activity as GSDME-deficient melanoma cells form and grow larger tumors than their wild-type (WT) counterparts." (PMID 30976076, 2019). "It suggested that iron could sensitize melanoma cells to ROS-induced drugs through GSDME and pyroptosis modulated pathways." (PMID 31616642, 2019). "Further studies have shown that the use of iron supplements in patients with iron deficiency can maximize the antitumor effect of clinical ROS-induced drugs, thereby inhibiting the growth and metastasis of xenografted melanoma cells through DFNA5/GSDME-dependent pyroptosis." (PMID 31501419, 2019). "Upon CCCP/iron stimulation, pyroptosis was observed in four other melanoma cell lines that expressed GSDME, regardless of the BRAF mutation status." (PMID 30287942, 2018). "This high GSDME expression may serve as an Achilles’ heel for melanoma, providing an opportunity for melanoma therapy via pyroptosis induction." (PMID 30287942, 2018). "Since iron activates ROS for GSDME-dependent pyroptosis induction and melanoma cells specifically express a high level of GSDME, iron may be a potential candidate for melanoma therapy." (PMID 30287942, 2018). "Therefore, iron sensitized melanoma cells to ROS-inducing drug therapy via GSDME- and pyroptosis-mediated pathways." (PMID 30287942, 2018).
melanoma (continued). "While in our previous work, we reported a platinum complex that induces pyroptosis in melanoma cells with high GSDME expression through Caspase‐3 cleavage of GSDME protein, no innovative platinum‐based drugs have yet been observed to produce similar effects in tumor cells with low GSDME expression." (PMID 40432601, 2025). "After treatment with BRAF/MEK inhibitors, melanoma cells lacking GSDME exhibited impaired infiltration of tumor-associated T cells, the number of activated dendritic cells was diminished, and a higher incidence of tumor regrowth after cessation of drug treatment was recorded." (PMID 38336727, 2024). "The DNA methylase inhibitor decitabine (5-aza-2'-deoxycytosine) could downregulate the expression of GSDME, thereby preventing the proliferation and colony formation ability of melanoma, gastric cancer and CRC cells, and may reduce the invasive ability of breast cancer cells." (PMID 36920176, 2023). "To illustrate, GSDME, a critical protein in the pyroptosis pathway, is usually expressed at high levels in normal tissues, but the abnormally elevated expression could occur in some tumors, including lung cancer, gastric carcinoma and melanoma." (PMID 37149620, 2023). "Notably, the efficacy of a BRAF-MEK inhibitor in eliminating melanoma is completely blocked in immunodeficient GSDME-positive mice, implying that the potential molecular mechanism of BRAF-MEK inhibitor treatment of melanoma is a GSDEM-dependent antitumour immune response." (PMID 35896522, 2022). "In addition to inducing ferroptosis, iron, an essential factor in ROS modulation, can enhance melanoma cell pyroptosis by promoting the cleavage of GSDME, which suggests that iron may be a promising sensitizer for ROS-induced melanoma treatment." (PMID 33665167, 2020). "GSDME expressed by the pyroptostic cell the combined treatment of BRAF and MEK inhibitors in melanoma can elevate the amount of T cells and DCs, while GSDME-deficient melanoma exhibited less HMGB1 release and BRAFi and MEKi resistance." (PMID 40064873, 2025). "Pretreatment with zVAD substantially reduced GSDME cleavage in melanoma cells following TRI-03 administration, confirming that TRI-03-stimulated GSDME cleavage is dependent on caspase activation." (PMID 40486906, 2025). "Epigenetic therapy can upregulate the expression of specific proteins, such as upregulating GSDME and ORZ levels using DNA methyltransferase inhibitor DAC, as well as upregulating GSDMD levels in melanoma." (PMID 39221221, 2024). "In diverse cancer lineages (colon and lung cancer, melanoma, and leukemia), the synergistic action of TNF-α and IFN-γ can trigger the activation of a variety of signaling switches such as GSDMD, GSDME, caspase-8, and MLKL." (PMID 38553639, 2024). "Knocking down IRF9 or STAT2 in melanoma cell lines A375 and SK-MEL-28 induces GSDME-dependent pyroptosis and restores sensitivity to BRAFi." (PMID 37373523, 2023). "For example, dual BRAF/MEK inhibition induces cleavage of pyroptosis marker gasdermin E (GSDME) and intra-tumoral T cell infiltration, but BRAFi/MEKi resistance attenuates these responses in melanoma." (PMID 37834284, 2023). "Recently, bidirectional regulation between CASP3 and GSDME has been demonstrated, and GSDMD has also been found to play a role in the pyroptosis of melanoma cells." (PMID 37373523, 2023). "Small molecule inhibitors of kinases such as MEK, BRAF, EGFR, ALK, and KRAS promoted GSDME cleavage by CASP3 and resulted in lung cancer and melanoma regression." (PMID 35964070, 2022). "GSDME deletion by CRISPR/Cas9 gene editing in various cell types has been generated, for example, murine melanoma cell line B16 and thymoma cell lone EG7-Ova." (PMID 35795683, 2022). "C1QB, CXCL9, CXCL10, DFNA5 (GSDME), FCGR1B, and PRAME were increased in melanoma, and SCGB1D2 was decreased in melanoma, compared to dysplastic nevi or nevi that progressed to melanoma." (PMID 35008167, 2021).
melanoma (continued). "Within the immune system broadly, a large number of genes were identified with known roles in cancer, including AIM2, C1QA, and DFNA5 (also known as GSDME), which have been identified to have a mechanistic role in melanoma tumor growth." (PMID 35008167, 2021). "Raptinal is not toxic in vivo and showed therapeutic efficacy in a melanoma model by activating GSDME-mediated pyroptosis." (PMID 40544161, 2025). "Pyroptosis can be triggered by caspase 1 in the canonical pathway, caspase 4/5/11 in the noncanonical pathway, or caspase 3/8 in GSDMC- or GSDME-expressing tumor cells, including melanoma cells." (PMID 38336727, 2024). "Alternatively, the gasdermin E (GSDME) gene, belongs to gasdermin superfamily, originally identified as deafness autosomal dominant 5 (DNFA5), can function as a tumor suppressor gene in colorectal, gastric, melanoma, and breast carcinomas." (PMID 35551332, 2022). "The expression of GSDME mRNA in the etoposide-resistant human melanoma cell line MeWo-Eto-1 was found to be significantly lower than that in its parent nonresistant human melanoma cell line MeWo." (PMID 35480866, 2022). "To further test if GSDME possesses a tumor suppressive activity in vivo, we utilized a mouse model of melanoma whereby WT C57BL/6J were subcutaneously injected with either WT or GSDME-KO B16-Ova melanoma cells and tumor growth was monitored over time." (PMID 30976076, 2019). "In etoposide-resistant melanoma cells, knockout of DFNA5/GSDME increased cell resistance to etoposide, while upregulation of DFNA5/GSDME expression increased the cell sensitivity to etoposide, suggesting that decreased-DNFA5 is related to the increase in etoposide resistance in melanoma cells." (PMID 31501419, 2019). "Iron may be a potential candidate for the treatment of melanoma because it activates ROS to induce DFNA5/GSDME-dependent pyroptosis and specifically induces high levels of DFNA5/GSDME expression in melanoma cells." (PMID 31501419, 2019). "Furthermore, DHN-induced GSDME cleavage in tumor tissues peaked at 24 hours after injection, which aligns with the observation that DHN induced pyroptosis after 24 hours in melanoma cells, indicating its prolonged therapeutic effect." (PMID 40663398, 2025). "Moreover, the GSDME protein levels in cancer cells are not as invariable as those in normal cells, and BRAF/MEK inhibitors can promote the cleavage of GSDME and the release of high-mobility group box 1 (HMGB1), which are markers of pyroptotic cell death in melanoma cells." (PMID 38336727, 2024). "Besides, the combination treatment with v-raf murine sarcoma viral oncogene homolog B1 (BRAF) inhibitors and MEK inhibitors promotes GSDME cleavage and HMGB1 release in melanoma cells, which activate dendritic cells and ultimately lead to the proliferation of T cells to exert its anti-tumor effects." (PMID 35462927, 2022).